MIRLET7A2 (microRNA let-7a-2)
Synonyms: hsa-let-7a-2; LET7A2; MIRNLET7A2; let-7a-2
Gene: MicroRNA gene on chromosome 11 (122,146,522 to 122,146,593, reverse strand). Ensembl gene ENSG00000198975.
Gene Ontology:
Biological process: miRNA-mediated post-transcriptional gene silencing
Cellular component: RISC complex
Homologues: Orthologues: chimpanzee ptr-let-7a-2 (100% identical), dog MIRLET7A2 (100% identical), guinea pig MIRLET7A2 (100% identical), macaque mml-let-7a-2 (99% identical), pig ssc-let-7a-1 (97% identical). Paralogues in human: MIRLET7C (88% identical), MIRLET7E (79% identical), MIRLET7A1 (72% identical), MIRLET7A3 (72% identical), MIRLET7F2 (71% identical), MIRLET7G (69% identical), MIRLET7D (68% identical), MIRLET7F1 (68% identical), MIR98 (67% identical), MIRLET7I (60% identical).
Diseases named in the same sentence as MIRLET7A2 in open-access papers:
MIRLET7A2 is named in the same sentence as 2 diseases in open-access papers, as found by Europe PMC text mining. Sharing a sentence is not in itself a finding about the gene and the disease. The quoted sentences say what the papers report.
cancer (1 paper, 2012). A tumor composed of atypical neoplastic, often pleomorphic cells that invade other tissues. "In OB/OW subjects three genes were consistently overexpressed (TC2N, MIRLET7A2 and CLDN10) in the PP adipose tissue of men with cancer (EPCa or OCPCa), compared to BPH." (PMID 23009291, 2012).
MIRLET7A2 also shares sentences with these, for which no sentence is quoted: teratospermia (1 paper).